CGA (glycoprotein hormones, alpha polypeptide)
Diseases named in the same sentence as CGA in open-access papers (continued):
Sharing a sentence is not in itself a finding about the gene and the disease.
insulinomas (continued). "CgA is a reliable serum diagnostic biomarker for PNETs but not for insulinomas." (PMID 25099181, 2014). "This is in line with current ENETS recommendations, where a single follow-up 3–6 months postoperatively with CgA measurement (if initially elevated) and no recurrent imaging is proposed for the specific pNEN subgroup “Insulinoma, solitary, G1–G2 NET”." (PMID 37386194, 2023). "A recent study demonstrated that insulin and proinsulin were released in patients with insulinomas in response to arterial calcium stimulation, whereas CgA was not released." (PMID 25099181, 2014). "The interesting finding in the study was that serum CgA levels were not elevated in patients with insulinomas, including one patient with extensive liver metastases (48 ng/ml)." (PMID 25099181, 2014). "Except for two insulinomas with negative staining of CgA, 12 insulinoma tissues showed positive staining of CgA." (PMID 25099181, 2014). "With a relatively low specificity (73%), serum CgA was not a reliable and practicable biomarker for diagnosis of insulinoma." (PMID 25099181, 2014). "In present study, we did not observe the correlation between the tumor size and CgA levels in PNETs (P = 0.545) and in insulinomas alone (P = 0.942)." (PMID 25099181, 2014). "We found that serum levels of CgA were not significantly elevated in patients with insulinomas, compared to the higher levels of CgA in other PNETs." (PMID 25099181, 2014). "Although the levels of CgA in patients with insulinomas were not elevated significantly, it was interesting that the serum levels of CgA were decreased in 16 of 17 patients with insulinomas after tumor resection (median 64.8 ng/ml vs. 50.4 ng/ml, P = 0.003)." (PMID 25099181, 2014). "In conclusion, our findings suggested that CgA is not a reliable biomarker for insulinomas, hence, examination of blood CgA levels could not be recommended in patients with insulinoms according to Nobels’ and our data." (PMID 25099181, 2014). "Because the serum CgA levels were not elevated in patients with insulinomas, we wanted to determine whether the protein of CgA was expressed in tumor tissues or not." (PMID 25099181, 2014). "Another study showed that CgA levels were not elevated in 5 cases of insulinomas." (PMID 25099181, 2014). "It maybe not necessary to test CgA levels in patients with insulinomas although this issue needs to be further validated in more cases and in multiple clinical centers." (PMID 25099181, 2014). "Two of 14 insulinomas and 1 of 12 non-insulinoma PNETs had very weak IHC staining of CgA protein." (PMID 25099181, 2014). "However, whether serum levels of CgA should be tested in patients with insulinomas has not been well clarified in those guidelines for NETs diagnosis." (PMID 25099181, 2014). "However, only small part of the protein might be secreted into blood by the insulinoma cells because the CgA levels were not elevated and, the CgA levels were significantly reduced in 16 patients after tumor resection (from median 64.8 ng/ml to median 50.4 ng/ml, P = 0.003)." (PMID 25099181, 2014).
lung carcinoma (6 papers, 2014 to 2025). "For example, an IHC panel that includes thyroid transcription factor-1 (TTF-1), Napsin A, CK5/6, p40, CD56, synaptophysin (Syn), and chromogranin (CgA) will be useful in the differentiation of the histological type of lung cancers." (PMID 34975346, 2021). "The lung cancer exhibited strong staining for NCAM1, NSE, Syn, and CgA, and the observed reductions in menin were associated with high Ki67 proliferation indexes in tumors." (PMID 32081882, 2020). "These biomarkers, including CYFRA 21-1, NSE, ProGRP, SCC, CEA, tumor M2-PK, CRP, LDH, tumor-suppressor genes, and oncogenes, CA125, CgA, NCAM, and TPA, are useful in the diagnosis and clinical management of lung cancer." (PMID 39195131, 2024).
periodontitis (6 papers, 2015 to 2025). An acute or chronic inflammatory process that affects the tissues that surround and support the teeth. "Other biomarkers evaluated were CgA, elastase (ng/mL), and ICTP (ng/mL) to assess the correlation between stress, type 1 collagen degradation, and bone loss caused by periodontitis, respectively." (PMID 40095650, 2025). "Previous studies showed a close relationship between psychological stress, salivary CgA and the extent of periodontitis." (PMID 38368525, 2024). "In a case-control study involving 30 subjects affected by chronic periodontitis and a control group comprising of 30 healthy patients, the levels of CgA in plasma saliva were determined by ELISA quantification." (PMID 31263455, 2019). "A significantly higher CgA amount was found in plasma salivary samples of individuals affected by chronic periodontitis respect to control patients." (PMID 31263455, 2019). "Several studies presented used saliva samples, cortisol, α-amylase, β-endorphin, chromogranin (CgA), salivary IgA, and various other reactive oxygen metabolites ROM to investigate their relationship to periodontitis." (PMID 37239803, 2023). "CgA is produced by human submandibular gland HSG and secreted into saliva and is present into inflamed pulp and in caries with concomitant mild periodontitis." (PMID 31263455, 2019).
acute coronary syndrome (5 papers, 2014 to 2023). Signs and symptoms related to acute ischemia of the myocardium secondary to coronary artery disease. "CgA measurement in cardiac patients has only been pursued in selected patient cohorts, mostly with ischemic heart disease (acute coronary syndromes)." (PMID 24532383, 2014).
Alzheimer disease (5 papers, 2014 to 2026). A progressive, neurodegenerative disease characterized by loss of function and death of nerve cells in several areas of the brain leading to loss of cognitive function such as memory and language. "CgA is known to be associated with protein aggregates in the brains of neurodegenerative diseases including Alzheimer’s disease (AD)." (PMID 40393970, 2025). "Dysregulation of CgA-derived peptides has been reported in cardiometabolic disease 17–19, immune regulation 15,20 and Alzheimer’s disease 21, however, their mechanistic role in neurodegeneration - particularly in Tauopathies - remains largely unexplored." (PMID 41509358, 2026). "This study investigates the role of CgA in Alzheimer’s disease (AD) and corticobasal degeneration (CBD)." (PMID 39149499, 2024). "Elevated serum CgA levels have been found in many cancers and neurodegenerative diseases, such as Alzheimer’s disease and Parkinson’s disease." (PMID 35062888, 2022).
Brain atrophy (5 papers, 2013 to 2025). Partial or complete wasting (loss) of brain tissue that was once present. "In particular, our first finding showed that several proteins were associated with brain atrophy and CSF biomarkers, however, levels of CgA and FABP emerged as the most consistently present across most our comparisons." (PMID 26284520, 2015). "Lower levels of CgA were associated with higher whole brain atrophy and ventricular expansion when t-tau and baseline volume were included in the model; and with higher whole brain atrophy when p-tau, age, APOE status and sex were also included as covariates." (PMID 25072324, 2014). "Lower levels of Chromogranin-A (CgA) were associated with higher whole brain atrophy (0.008) and ventricular expansion (0.009) after adjusting for baseline volumes and t-tau and predicts higher whole brain atrophy (P=0.009) after additionally adjusting for p-tau, age, ApoE status and sex." (PMID 25072324, 2014). "Next, we determined the potential role of CgA depletion in attenuating neuroinflammation, a key contributor to neurodegeneration and subsequent brain atrophy in PS19 mice." (PMID 40393970, 2025). "Next, we determined the potential role of CgA depletion in attenuating neuroinflammation, a key contributor to neurodegeneration and subsequent brain atrophy in hTau mice." (PMID 39149499, 2024). "In this study, we found an association between AD-like patterns of brain atrophy, quantified by the SPARE-AD index, and plasma cortisol, CgA, IGFBP-2 and MIP-1α levels." (PMID 23408997, 2013). "In contrast, CgA-KO/PS19 mice exhibited minimal brain atrophy." (PMID 40393970, 2025). "In contrast, CgA-KO/hTau mice exhibited minimal brain atrophy." (PMID 39149499, 2024). "We found that several proteins (primarily CgA and FABP) were related to either brain atrophy or CSF biomarkers." (PMID 26284520, 2015).
chronic heart failure (5 papers, 2014 to 2025). "Circulating CgA levels correlate with serum inflammatory markers like C-reactive protein (CRP), procalcitonin, IL-1β, IL-6, IL-8/CXCL8, IL-17C, or TNF in conditions such as gastritis, IBD, chronic heart failure or systemic inflammatory response syndrome." (PMID 40370467, 2025).
depression (5 papers, 2008 to 2025). "CP2305 supplement also significantly improved sleep quality (PSQI) and lowered depressions scores (GHQ-28) which corresponded with reduced salivary CgA levels." (PMID 36364881, 2022). "The depression group had significantly higher plasma CgA level (median 145.60 vs 82.40, P < .001)." (PMID 32515855, 2020). "A correlation between CgA secretion and the depression score was observed in this study." (PMID 18983682, 2008).
gastroenteropancreatic neuroendocrine tumors (5 papers, 2013 to 2022). "Chromogranin A (CgA), present in the chromaffin granules of neuroendocrine cells, is a useful biomarker for the diagnosis of patients with gastroenteropancreatic neuroendocrine tumors (GEP-NETs)." (PMID 27159453, 2016). "Chromogranin A (CgA) and the Ki-67 proliferation index are considered as important biochemical and pathological markers for clinical behaviour of gastroenteropancreatic neuroendocrine tumors (GEP NETs), respectively." (PMID 24042314, 2013). "Thus, the combined post-protein-meal serum CgA and PP measurement will increase the early detection of gastroenteropancreatic NETs (GEP-NETs)." (PMID 32020844, 2020). "The expression of CgA is widely used to identify gastrointestinal NETs." (PMID 25886790, 2015).
Medullary thyroid carcinoma (5 papers, 2020 to 2025). "Immunohistochemistry (ELISON method) showed: in the medullary carcinoma area: PCK (+), CEA (+), CT (focal cytoplasmic weak +), INSM1 (+), Syn (+), CgA (+), Galectin-3 (-), TG (-), CK19 (-), Ki-67 (+, 3%)." (PMID 41323380, 2025). "Medullary thyroid carcinoma (MTC) is a rare thyroid carcinoma of C-cell deviation that produces and secretes calcitonin (CT) and chromogranin A (CgA) into the blood." (PMID 33485291, 2021).
pulmonary neuroendocrine tumor (5 papers, 2019 to 2025). "Beyond the scope of panNETs, in one patient, increased CgA led to earlier detection of recurrent inoperable lung NET." (PMID 40455177, 2025). "In the third case, increased CgA (1.1 times ULN) in a patient previously treated for lung NET prompted a repeat measurement of CgA 6 months later." (PMID 40455177, 2025). "Because SCLC originates from neuroendocrine cell precursors, it expresses neuroendocrine markers such as Syn and CgA, therefore, it is classified as a type of pulmonary neuroendocrine tumor." (PMID 37583423, 2023). "The aim of this study was to evaluate the diagnostic effectiveness of pro-gastrin-releasing peptide (ProGRP) and chromogranin A (CgA) in the diagnosis of neuroendocrine neoplasms of the lung (LNENs), (290 cases) and compared these results with controls (54 cases)." (PMID 37444393, 2023). "Lung NETs are encountered in approximately 20% of patients with MEN1, and are potentially responsible for elevated CgA." (PMID 40455177, 2025). "As CgA increased further (48% rise, to 1.6 times ULN), SSTR PET/CT was conducted, the patient was diagnosed with recurrent inoperable lung NET, and SSA treatment was initiated, leading to a single significant alteration in clinical management in this patient population." (PMID 40455177, 2025). "Comparisons of pulmonary neuroendocrine tumors (PNET) and other groups with ROC analysis in terms of progastrin-releasing peptide (ProGRP), neuron-specific enolase (NSE), adjusted NSE, chromogranin A (CgA), and squamous cell carcinoma antigen 1 (SCCA1) values." (PMID 31091854, 2019). "Progastrin-releasing peptide (ProGRP), neuron-specific enolase (NSE), NSE adjusted, chromogranin A (CgA), and squamous cell carcinoma antigen 1 (SCCA1) values in the pulmonary neuroendocrine tumors (PNET), non-small-cell lung carcinoma (NSCLC), benign, and healthy groups." (PMID 31091854, 2019). "While some evidence suggests that SSTR PET/CT has good diagnostic capability in detecting lung NETs, and our local surveillance protocols include thoracic CT at least every five years, we cannot rule out the possibility of undiagnosed lung NETs interfering with the CgA measurements." (PMID 40455177, 2025).
Sepsis (5 papers, 2015 to 2025). Sepsis is defined as life-threatening organ dysfunction caused by a dysregulated host response to infection. "It was previously reported the role of this protein as biomarker for mortality in Intensive Care Unit (ICU) patients with sepsis showing that higher CgA plasma levels were associated to mortality." (PMID 36090980, 2022). "Measurement of CgA is useful for diagnostic and predictive purposes in various syndromes and diseases in humans such as sepsis, neuroendocrine tumors and heart disease." (PMID 25636335, 2015). "Because this is the first report of CgA in a disease related to sepsis in dogs, the diagnostic and predictive value of CgA needs to be further studied for such evaluation to be possible." (PMID 25636335, 2015). "Several studies have shown that concentrations of stress-related neurochemicals, e.g. catecholamines that are released together with CgA, increase in sepsis." (PMID 25636335, 2015). "Plasma levels of VS-I were found gradually increased in patients with sepsis, severe sepsis and septic shock in comparison to healthy controls, also indicating in this setting that plasmatic VS-I is more sensitive and specific for the evaluation of sepsis and its severity than CgA measurement." (PMID 36090980, 2022). "The value of CgA and its products when measured in dogs with sepsis remains to be determined." (PMID 25636335, 2015).
small cell lung carcinoma (5 papers, 2018 to 2025). Small cell lung cancer (SCLC) is a highly aggressive malignant neoplasm, accounting for 10-15% of lung cancer cases, characterized byrapid growth, and early metastasis. "Thus 4E5 mAb can be used to specifically recognize CgA in the small cell lung carcinomas (SCLC), adrenal gland tissues, and Islet cell carcinoma." (PMID 29728076, 2018). "Histochemistry showed TTF-1 was positive, CgA was paranuclear punctate positive, and the urothelial marker GATA3 was negative, which well proved that the source of the kidney tumor in this case was lung small cell carcinoma." (PMID 37161448, 2023). "The average CgA level in small cell lung cancer (SCLC) is higher compared to the control group, while in the case of bronchial NENs, the CgA concentration is lower compared to other types of NENs and, importantly, may be comparable to the values found in other non-cancerous diseases." (PMID 39451760, 2024).
squamous carcinoma (5 papers, 2019 to 2025). "Less differentiated squamous cell carcinoma specifically expresses vimentin as well as CK and CK5/6 but not CK20, CK7, and neuroendocrine markers (including CD56, CgA, and Syn)." (PMID 41245381, 2025). "CK5/6, P40 and P63 were all positive (100%) in the detected LELC and squamous carcinoma samples; in parallel, TTF-1, CgA and Syn were negative without exception." (PMID 31752892, 2019).
tauopathy (5 papers, 2024 to 2026). Neurodegenerative disorders involving deposition of abnormal tau protein isoforms (tau proteins) in neurons and glial cells in the brain. "The effects of CgA on metabolism and aging, together with CgA’s association with the central nervous system (CNS) and AD prompted us to investigate the role of CgA in the pathophysiology of Tauopathy." (PMID 40393970, 2025). "Collectively, these findings suggest that upregulated Adra1 and compromised Adra2 signaling underlies CgA’s detrimental effect in Tauopathy brain." (PMID 40393970, 2025). "Together, these findings establish a validated murine model of AsymAD and identify CgA as a modifiable molecular node linking neuroendocrine signaling, Tauopathy, and cognitive preservation." (PMID 41935326, 2026). "We demonstrate that Tauopathies are characterized by a marked reduction in the neuroprotective CgA-derived peptide CST, accompanied by a reciprocal increase in PST, in human AD, CBD, and PSP." (PMID 41509358, 2026). "CgA ablation in Tauopathy mice (PS19) (CgA-KO/PS19) reduced pathological Tau aggregation and spreading, extended lifespan, and improved cognitive function." (PMID 40393970, 2025). "We discovered that in Tauopathy brains, there are elevated levels of CgA, EPI, and aberrant Adra signaling." (PMID 40393970, 2025). "Chromogranin A (CgA) ablation in Tauopathy mice reduces toxic Tau buildup, reverses cognitive decline and improves lifespan." (PMID 40393970, 2025). "Our recent work demonstrated that CgA deletion in PS19 Tauopathy mice (CgA-KO/PS19) reduces Tau burden, delays disease progression, and improves behavioral outcomes." (PMID 40661391, 2025). "Collectively, these findings suggest that CgA-driven exaggerated Adra1 and compromised Adra2 signaling constitute a key event in tauopathy and related dementia, including AD." (PMID 39149499, 2024). "CgA ablation in tauopathy mice (hTau) (CgA-KO/hTau) exhibited reduced tau aggregation, spreading, extended lifespan, and improved cognitive function." (PMID 39149499, 2024). "A recent study reported increased CgA in the cerebrospinal fluid (CSF) of AD patients, which correlated with phosphorylated Tau (p-Tau) and Tau levels, implicating a potential link between Tauopathy and CgA33." (PMID 40393970, 2025). "We also observed that in Tauopathy brains, CgA and aggregated Tau are partially colocalized, which could initiate non-physiological processes such as diminished axonal transport, EPI storage and release." (PMID 40393970, 2025). "We hypothesized that depleting CgA could enhance longevity and ameliorate Tauopathy." (PMID 40393970, 2025). "This study uncovers previously unexplored roles of CgA and EPI in the pathogenesis of Tau in the brains of Tauopathies, including AD, CBD and mouse models." (PMID 40393970, 2025). "Treatment with CgA (5 ng/ml) led to marked accumulation of misfolded Tau species detected by MC1 antibody, confirming CgA-mediated augmentation of Tauopathy." (PMID 40393970, 2025). "This study uncovers previously unexplored roles of CgA and EPI in the pathogenesis of tauopathies including AD, CBD and mouse models." (PMID 39149499, 2024).